YWHAQ (tyrosine 3-monooxygenase/tryptophan 5-monooxygenase activation protein theta)
Description:
Adapter protein implicated in the regulation of a large spectrum of both general and specialized signaling pathways. Binds to a large number of partners, usually by recognition of a phosphoserine or phosphothreonine motif. Binding generally results in the modulation of the activity of the binding partner. Negatively regulates the kinase activity of PDPK1.
Synonyms: HS1; 14-3-3; 1C5
Tractability: Small molecule: it has a high-quality binding pocket. PROTAC: UniProt records ubiquitination sites on it; ubiquitination databases record sites on it; its protein half-life has been measured.
Gene: Protein-coding gene on chromosome 2 (9,583,967 to 9,639,472, reverse strand). Ensembl gene ENSG00000134308.
Subcellular location: Cytoplasm
Subcellular location (Human Protein Atlas): Cytosol; Nucleoli rim; Nucleoplasm
Pathways (Reactome):
Disease: SARS-CoV-1 targets host intracellular signalling and regulatory pathways; SARS-CoV-2 targets host intracellular signalling and regulatory pathways
Gene expression (Transcription): Regulation of localization of FOXO transcription factors
Cell Cycle: Chk1/Chk2(Cds1) mediated inactivation of Cyclin B:Cdk1 complex
Programmed Cell Death: Activation of BAD and translocation to mitochondria
Signal Transduction: RHO GTPases activate PKNs
Vesicle-mediated transport: Translocation of SLC2A4 (GLUT4) to the plasma membrane
Gene Ontology:
Molecular function: identical protein binding; protein binding; 14-3-3 protein binding; protein domain specific binding; transmembrane transporter binding
Biological process: negative regulation of DNA-templated transcription; substantia nigra development; intracellular protein localization; negative regulation of monoatomic ion transmembrane transport
Cellular component: cytoplasm; cytosol; extracellular exosome; focal adhesion; membrane; nucleus; protein-containing complex; synapse
Genetic constraint (gnomAD): Loss-of-function variants: 6 observed, 26 expected, observed/expected ratio (o/e) 0.23, 90% interval 0.12 to 0.46. The upper end of that interval is the gene's LOEUF score, 0.46, which puts it in group 2 of 6, group 1 being the genes least tolerant of losing a copy. Missense variants: 200 observed, 315.71 expected, observed/expected ratio (o/e) 0.63, 90% interval 0.56 to 0.71. Synonymous variants: 143 observed, 126.98 expected, observed/expected ratio (o/e) 1.13, 90% interval 0.98 to 1.29.
Homologues: Orthologues: chimpanzee YWHAQ (100% identical), dog YWHAQ (100% identical), guinea pig YWHAQ (100% identical), macaque YWHAQ (100% identical), pig YWHAQ (91% identical), zebrafish ywhaqb (83% identical), zebrafish ywhaqa (82% identical), Drosophila melanogaster 14-3-3zeta (77% identical), Caenorhabditis elegans par-5 (75% identical), Caenorhabditis elegans ftt-2 (70% identical). Paralogues in human: YWHAB (81% identical), YWHAZ (80% identical), YWHAH (71% identical), SFN (70% identical), YWHAG (70% identical), YWHAE (66% identical).
Diseases named in the same sentence as YWHAQ in open-access papers:
YWHAQ is named in the same sentence as 165 diseases in open-access papers, as found by Europe PMC text mining. Sharing a sentence is not in itself a finding about the gene and the disease. The quoted sentences say what the papers report.
breast carcinoma (24 papers, 2010 to 2023).
schizophrenia (19 papers, 2011 to 2025). A major psychotic disorder characterized by abnormalities in the perception or expression of reality. "Moreover, an increased expression of SFN and decreased expression of YWHAB, YWHAE, YWHAG and YWHAQ mRNA have been reported in leukocytes of schizophrenia patients." (PMID 32545830, 2020). "All three sets of module genes include well-studied candidate genes for schizophrenia (e.g., DTNBP1), glutamate receptors (e.g., GRIN1), several genes located in the MHC region (e.g., HIST1H1A, HIST1H1C, HIST1H2AB, HIST1H2BB, HLA-E), and genes from the 14-3-3 protein family (e.g., YWHAQ, YWHAZ)." (PMID 23134571, 2012).
lung carcinoma (7 papers, 2015 to 2024). "Thus, the YWHAB, YWHAQ, and YWHAZ proteins involved in various biological processes and signalling pathways, could be new targets for future cancer therapy, especially in targeting CSCs in lung cancer." (PMID 33670440, 2021).
Obesity (5 papers, 2013 to 2025). Accumulation of substantial excess body fat. "We detected five genes were different expressed, YWHAQ, NCF2, DHRS9 and SCNA only up-regulation in PCOS-obesity patients with no significance different between control and PCOS-nonobesity patients." (PMID 27056885, 2016). "YWHAQ, NCF2, DHRS9 and SCNA were up-regulation in PCOS-obesity patients with no significance different between control and PCOS-nonobesity patients, which may be activated by lower DNA methylaiton." (PMID 27056885, 2016).
epilepsy (4 papers, 2017 to 2025). A brain disorder characterized by episodes of abnormally increased neuronal discharge resulting in transient episodes of sensory or motor neurological dysfunction, or psychic dysfunction. "The remaining group of functional proteins, including YWHAB, YWHAE, YWHAQ, and YWHAZ, that contribute to epilepsy turn out to be encoded by the so-called 14-3-3 family of proteins." (PMID 28255556, 2017).
amyotrophic lateral sclerosis (3 papers, 2011 to 2024). Amyotrophic lateral sclerosis (ALS) is a neurodegenerative disease characterized by progressive muscular paralysis reflecting degeneration of motor neurons in the primary motor cortex, corticospinal tracts, brainstem and spinal cord. "In addition, YWHAQ is upregulated in patients with amyotrophic lateral sclerosis (ALS)." (PMID 39061176, 2024).
cancer (108 papers, 2005 to 2025). A tumor composed of atypical neoplastic, often pleomorphic cells that invade other tissues. "The colorectal cancer related protein PABPC4 of the SARS-CoV-2 interactome interacts with YWHAQ, YWHAZ & TNFRSF10D that all involve Apoptosis59." (PMID 36463386, 2022). "DAVID functional annotation had selected only 4 out of 16 pathways in the A549 CD166 + EpCAM + CSC subpopulation, and 3 pathways in the A549 CD166-EpCAM– non-CSC subpopulation that were related to cancer diseases and that involved the proteins YWHAB, YWHAQ, and YWHAZ." (PMID 33670440, 2021).
tumor (71 papers, 2007 to 2025). "This is the case of KIF23, which was a hub gene in M2-tumor-associated macrophages, and it showed a higher expression level in tumor tissues, similarly to YWHAQ and AGRN." (PMID 40136513, 2025). "In addition, YWHAZ and YWHAQ were also selected for further analysis since these CB-NK proteins were identified either in 1°MM or 2°MM cells and are involved in tumor cell survival." (PMID 31619273, 2019). "In HER2− tumours, baseline expression of 48 genes associated with poor antiproliferative response (p < 0.005) including PERP and YWHAQ, the two most significant, and the transcription co-regulators (SAP130, HDAC4, and NCOA7) which were among the top 16 most significant." (PMID 31892336, 2019). "Interestingly, RFX5 mRNA has previously been shown overexpressed in HCC compared with non-tumor tissue, which promoted HCC progression via transcriptionally activating KDM4A, TPP1 and YWHAQ." (PMID 37008925, 2023). "Furthermore, the expression of YWHAQ and NEK2 was significantly higher in luminal B compared to luminal A tumours in TCGA ER+/HER2− tumours." (PMID 31892336, 2019). "Many of these genes, including those encoding bFGF, MAPK10, MAP3K5, IL1R2, E-cadherin, Ki67, Cyclin E1, beta-catenin, 14-3-3 protein T-cell (YWHAQ), integrin alpha-V (ITGAV), integrin alpha-10 (ITGA10), CDK6, PCNA, CDKN1A, and PAK3, are related to tumor metastasis and regulation of cell migration." (PMID 28454092, 2017). "Among all selected prognostic biomarkers, ESR1, PGR, BRTC, YWHAQ and PLK1 were recognized as crucial features; for clinical features, whether the patient has gone through chemotherapy/hormone therapy and the size of the tumor play an important role in model predictions." (PMID 36698767, 2023).
YWHAQ also shares sentences with these, for which no sentence is quoted: neurodegenerative disease (29 papers); infection (26); neurological disorders (20); Parkinson disease (20); Alzheimer disease (19); Creutzfeldt-Jakob disease (19); prion disease (11); dementia (9); virus infection (9); Stroke (8); metabolic disease (6); colorectal cancer (5); glioma (5); hepatocellular carcinoma (5); melanoma (5); Myoclonus (5); pancreatic cancer (5); sporadic Creutzfeldt-Jakob disease (5); brain cancer (4); brain diseases (4); colon cancer (4); demyelinating disease (4); diabetes (4); gastric cancer (4); Hypertension (4); ovarian carcinoma (4); prostate carcinoma (4); psychiatric disorder (4); toxoplasmosis (4); Ataxia (3).
A further 127 diseases each share a sentence with YWHAQ in 3 papers or fewer.